ARID1A (AT-rich interaction domain 1A)
Diseases named in the same sentence as ARID1A in open-access papers (continued):
Sharing a sentence is not in itself a finding about the gene and the disease.
ovarian carcinoma (continued). "Loss of ARID1A is higher in atypical endometriosis and non-atypical endometriosis adjacent to ovarian cancer than non-atypical endometriotic distal lesions." (PMID 30087267, 2018). "Furthermore, inhibition of the EZ2H methylesterase in ARID1A mutated ovarian cancer cells results in synthetic lethality, suggesting EZ2H as a potential new therapeutic target for ARID1A mutated tumours." (PMID 30104481, 2018). "Recently, ARID1A deficiency was shown to be associated with increased CD8 T-cell infiltration and expression of programmed death-ligand 1 (PD-L1) in ovarian cancer, implying the potential of ARID1A as a predictor of response to immune checkpoint inhibitors (ICIs)." (PMID 30400822, 2018). "Loss of ARID1A protein expression is frequently associated with PI3K/AKT pathway activation by which to promote the development of cancer, especially endometriosis-associated ovarian cancers." (PMID 26909602, 2016). "Although the drug sensitivity of ARID1A-deficiency has been analyzed in ovarian cancer cell lines, no in vivo effectiveness of PI3K/AKT inhibitors for GC cells with ARID1A depletion has been addressed." (PMID 27323812, 2016). "In ovarian cancer, ARID1A deficiency alone is not sufficient for promoting tumorigenesis, it requires PIK3CA co-activation." (PMID 26569409, 2015). "Endometrioid ovarian carcinomas show broad morphological similarities to their endometrial counterparts with the most common molecular alterations in endometrioid OC including mutations in CTNNB1 (31–53.3%), PIK3CA (15–40%), ARID1A (30%), and PPP2R1A (7–16.6%)." (PMID 41153668, 2025). "However, a mouse experiment revealed that the sole loss of ARID1A gene function does not induce ovarian cancer." (PMID 38725626, 2024). "In addition, ARID1A deficiency was associated with a higher TMB, more infiltrating lymphocytes, and increased PD-L1 expression in various tumours.Moreover, mice with ARID1A-deficient ovarian cancers showed a prolonged survival rate when treated with ICBs." (PMID 38166741, 2024). "However, decreased expression or Arid1a mutational status did not impact overall survival in patients with various types of ovarian cancer." (PMID 39123453, 2024). "The loss of ARID1A has been linked to the activation of MAPK signalling, sensitivity to PI3K/AKT/mTOR inhibitors and ATR inhibitors, as well as aurora kinase inhibition, warranting further investigation for the development of molecularly targeted therapies against ARID1A-mutated ovarian cancers." (PMID 39272926, 2024). "Thus far there has been a lack of clarity on its prognostic role in ovarian carcinomas, with previous reports showing conflicting or lack of association between ARID1A status and clinical outcome." (PMID 35647895, 2022). "There is little information regarding the influence of FRBI on ARID1A, PTEN, and FSHR associated with ovarian cancers and no quantitative research has been reported about the correlation between ovarian carcinogenesis and levels of ARID1A and PTEN in humans and animals." (PMID 31241714, 2019). "However, the accuracy of IHC as a predictor of ARID1A mutation in ovarian carcinoma has not been precisely defined as there is no uniform scoring system or specific antibody that is recommended for clinical IHC use." (PMID 29659191, 2018). "This demonstrates that even very frequent and potential cancer driving mutations such as PTEN and ARID1A in endometrioid endometrial and ovarian cancer may not be found in distant metastases, a fact that is essential for potential future targeted therapies." (PMID 28103826, 2017). "Recent research has highlighted that, similar to many other cancers, ovarian cancer is marked by alterations in a range of epigenetic regulators, including EZH2, SMARCA2/4, and ARID1A." (PMID 39605897, 2024). "In the treatment of ovarian cancer, the combination of temozolomide and a PARP inhibitor exploits the specific DNA damage repair status of ARID1A-inactivated ovarian cancers to suppress tumor growth." (PMID 39246656, 2024).
ovarian carcinoma (continued). "The ARID1A/PIK3K/AKT pathway in endometriosis and ovarian cancer regulates the proliferation and survival of endometriotic and cancer cells." (PMID 39684461, 2024). "Although single agent dasatinib has minimal activity in ovarian cancer clinical trial, a current trial assessing clinical activity of dasatinib includes OCCC patients and their ARID1A expression status (NCT02059265)." (PMID 37087441, 2023). "Other amplified oncogenes frequently found in epithelial ovarian cancer were ERBB2, STAT3, PIK3C2B, CDK2, and CDK4, as well as SWI/SNF chromatin modification complex genes, including ARID1A and SMARCC1." (PMID 36430324, 2022). "In recent years, it has become clear that, like the majority of other cancers, many epigenetic regulators are altered in ovarian cancer, including EZH2, SMARCA2/4 and ARID1A." (PMID 34213777, 2021). "The increase in mitochondrial content followed by the knockdown of ARID1A was accompanied by an increase in the expression levels of c-Myc in both ES-2 and RMG1 ovarian cancer cell lines." (PMID 33947138, 2021). "In most cases, ARID1A has emerged as a cancer suppressor in a broad array of cancers, such as HCC and ovarian carcinoma." (PMID 34671561, 2021). "In another study that used robust Bayesian network modeling, 13 hub genes including ARID1A, C19orf53, CSKN2A1, and COL5A2 signature with a prognostic function in ovarian cancer was established." (PMID 34054929, 2021). "Moreover, recent data reported by Shen and colleagues correlate loss-of-function mutations in ARID1A with the efficacy of anti-PD1 therapy, as a result of enhanced intratumoral lymphocyte recruitment and up-regulation of PD-L1 in preclinical models of ovarian cancer." (PMID 33578810, 2021). "Also, the loss of ARID1A-encoded protein BAF250a (a subunit of the Brahma-associated factor [BAF] nucleosome remodeling complex) was recorded as a frequent event in both ovarian clear cell and endometrioid carcinomas or in endometriosis-associated ovarian carcinomas." (PMID 31731647, 2019). "The synthetic lethality of ARID1A and AURKA was verified in three different ARID1A isogenic CRC pairs and three ovarian cancer cell lines with different ARID1A statuses; however, the synthetic lethality in ovarian cancer cells needs to be further investigated." (PMID 30097580, 2018). "We found that depletion of ARID1A using siRNA in ARID1A-wildtype RMG1 and OVCA432 ovarian cancer cells resulted in increased sensitivity to elesclomol." (PMID 27486766, 2016). "al., showed that cultured and primary ovarian cancer cells lacking ARID1A expression have low SLC7A11, a downstream target of NRF2, resulting in specific vulnerability to inhibitors of the GSH metabolic pathway." (PMID 38358974, 2024). "Some preclinical data suggest that inhibition of EZH2 may be effective in ovarian cancer, and mechanistically, inhibition of EZH2 histone methyltransferase activity is synthetically lethal in ARID1A mutant cancers." (PMID 39697230, 2024). "Additionally, the DUF3518 domain of ARID1A was found to be functionally necessary to antagonize EZH2, and both the R1989* variant and the deletion of the DUF3518 domain could not rescue EZH2-mediated IFN-γ signaling gene repression in ARID1A-knockout ovarian cancer cells." (PMID 36371186, 2022).
ovarian carcinoma (continued). "Thus, ARID1A and other SWI/SNF factors are likely to function epigenetically as a tumor suppressor for the development of ovarian cancer." (PMID 33917230, 2021). "Finally, we present the co-distribution of alterations of ARID1A genes and alterations of the PI3K pathway genes in tumors from patients with ovarian cancers enrolled at the Avera Cancer Institute." (PMID 31731647, 2019). "The downstream effector of the HIPPO pathway, TAZ, is expressed in ovarian cancers without ARID1A indicating that TAZ inhibitors could be used to induce synthetic lethality or an agonist that promotes ARID1A expression." (PMID 40429787, 2025). "Deleting the ARID1A gene alone does not induce ovarian cancer in mice, but when the ARID1A and PTEN genes are simultaneously knocked out, 60% of mice develop ovarian cancer with intra-abdominal dissemination, and 40% exhibit excessive proliferation of ovarian epithelium." (PMID 38725626, 2024). "Furthermore, empirical evidence from syngeneic mouse models demonstrates that ARID1A‐deficient ovarian cancer cells lead to a marked escalation in TILs and CD8 protein clusters, as opposed to their ARID1A‐wild‐type counterparts." (PMID 38374872, 2024). "Aberrant genes are a link between endometriosis and ovarian cancer; multipotent stem/progenitor cells show aberrant expression of genes such as KiT, HIF2 (hypoxia-inducible factor 2), and E-cadherin, and downregulation of the tumor-suppressor genes PTEN and ARID1A." (PMID 39684461, 2024). "Finally, to determine if the genes that display altered mRNA expression levels in ovarian cancer patient samples (PIK3CA, TTN, RYR2, KMT2C, KRAS, PTEN, and ARID1A) have any clinical value, we checked the effect of their expression on recurrence and survival of patients with ovarian cancer." (PMID 32626534, 2020). "Furthermore, Arid1a mutant, but not wild-type, ovarian cancer cell lines are also sensitive to reduction of EZH2." (PMID 31123059, 2019). "They measured oxidative stress through the activity of the antioxidant enzyme manganese dismutase (MnSOD), malondialdehyde (MDA), and ARID1A gene expression in tissue samples from patients with endometriosis, EAOC or nonendometriosis-associated ovarian cancer (non-EAOC)." (PMID 29743986, 2018). "Interestingly, SNVs in PTEN (p.Cys124Ser and p.Ala126Thr) and PTPRT (p.Val1429Met), and one-base indels in RAF1 (p.Met350fs) and ARID1A (p.Arg1053fs) were shared by the endometrial and ovarian carcinomas but not found in the lung metastasis." (PMID 28103826, 2017). "In addition, important cellular modulators, such as non-coding RNAs, Ets-1, CEBPG, ARID1A, SNAI2 and HRD1, could significantly regulate SLC7A11 expression in ovarian cancer cells, suggesting that these modulators could be potential therapeutic targets in ovarian cancer patients." (PMID 38203758, 2024). "As the field advanced, a synthetic lethal relationship was described with mutant ARID1A, a member of the SWI/SNF chromatin remodeling complex, in ovarian cancer, where EZH2 silences autophagy in the absence of functional ARID1A." (PMID 34691767, 2021). "Given the importance of these pathways in a broad range of cancer types, including colorectal and epithelial ovarian cancer profiled in this study, our data argue for SWI/SNF inhibition as a potential therapeutic approach for ARID1A mutant cancers independent of cancer type." (PMID 28967863, 2017).
ovarian clear cell cancer (173 papers, 2010 to 2026). An invasive malignant neoplasm that arises from the ovary and is characterized by a predominance of clear and hobnail malignant epithelial cells. "Previous literature has determined ovarian clear cell carcinoma was the most common cancer type found with an ARID1A mutation, with endometrioid cancer being the second." (PMID 40429787, 2025). "One study found that in ovarian clear cell carcinoma, there was an ARID1A mutation in 46–57% of tumors." (PMID 40429787, 2025). "ARID1A-deficient ovarian clear cell carcinoma is a highly lethal gynecologic cancer that depends heavily on mitochondrial respiration." (PMID 40564930, 2025). "The frequent co-occurrence of ARID1A loss with PIK3CA mutations in various cancers, including TNBC, ovarian clear cell carcinoma, and cholangiocarcinoma, highlights the vital role of ARID1A and PI3K/AKT in tumorigenesis." (PMID 41514650, 2025). "Approximately 33% of ovarian clear cell carcinoma cases exhibit co-mutations of ARID1A and PIK3CA, which activate pro-inflammatory cytokine genes via the NF-kB pathway, thereby promoting tumor growth." (PMID 41514650, 2025). "ARID1A is one of the highest mutated genes in many adult cancers including ovarian clear cell carcinoma, hepatocellular carcinoma, uterine carcinoma, as well as gastric, pancreatic, breast, colon, and lung cancer 18,22." (PMID 40082458, 2025). "We identified a cancer stress response regulator called KEAP1 as a potential target for ARID1A-deficient ovarian clear cell carcinomas." (PMID 39272807, 2024). "Worth mentioning that the mutation of the hTERT promoter seems not to be present at the beginning of oncogenesis and appears to be linked with the lack or downregulation of ARID1A, a tumour suppressor gene, in ovarian clear cell carcinomas (OCC)." (PMID 37548940, 2024). ", about 40-50% of ovarian clear cell carcinoma cases harbor loss-of-function mutations in ARID1A, a tumor suppressor and part of the SWI/SNF chromatin remodeling complex." (PMID 38836164, 2024). "The frequency of ARID1A loss varies between cancer subtypes, with clear cell ovarian carcinoma (CCOC) presenting the highest incidence at > 50% of cases." (PMID 39272807, 2024). "Gemcitabine is effective in ARID1A-mutated ovarian clear cell carcinoma cell lines and OCCC patients." (PMID 39697230, 2024). "Preclinical data suggest a synthetic lethal interaction between targeted ATR therapy and ARID1A deletion mutations in ovarian clear cell carcinoma and other cancer cell lines." (PMID 39697230, 2024). "With regards to ovarian clear cell carcinomas, the screening for mutations in the genes of ARID1A, PIK3CA, and ZNF217, can be judged as an inadequate prognostic marker." (PMID 37548940, 2024). "ARID1A subunit mutations are present in more than 50% of ovarian clear cell carcinomas and 40% of endometrioid carcinomas." (PMID 39609317, 2024). "It was shown that switching SMARCA4 to SMARCA2 induced acquired resistance to EZH2 inhibitors in ARID1A-mutated ovarian clear cell carcinoma." (PMID 39697230, 2024). "Researchers identified ARID1A mutations in 43–57% of ovarian clear cell carcinomas and 30% of ovarian endometrioid carcinomas." (PMID 38391958, 2024). "It is widely accepted that the two most frequent and important gene alterations in ovarian clear cell carcinoma occur in ARID1A and PIK3CA (both are mutated in ~ 50% of cases)." (PMID 38573494, 2024). "GLS-1 inhibition alone or in combination with immune checkpoint blockade represents an effective therapeutic strategy for SWI/SNF-altered cancers such as ARID1A-mutated ovarian clear cell carcinoma." (PMID 38383406, 2024). "The most durable response was in a patient with clear cell ovarian carcinoma and an ARID1A mutation (E21763fsX) with loss of protein expression." (PMID 37934611, 2024).
ovarian clear cell cancer (continued). "ARID1A is mutated in ~8% of all cancers, with clear cell ovarian carcinoma (CCOC) presenting the highest incidence of ARID1A loss at > 50% of cases." (PMID 39272807, 2024). "Instead, mutations are present in genes other than HGSOC, such as ARID1A (characteristic of endometrioid and clear cell ovarian cancer) and PIK3CA (identified in clear cell ovarian cancer)." (PMID 37886943, 2023). "ARID1A, an epigenetic tumor suppressor, is the most common gene mutation in clear-cell ovarian cancers (CCOCs)." (PMID 37841875, 2023). "In endometrial cancer, ovarian clear cell carcinoma, colon cancer, and gastric cancer, loss of ARID1A expression stimulates Akt1 phosphorylation." (PMID 36910637, 2023). "Although primary endpoint of the trial failed, ENMD-2076 showed an improved outcome in ARID1A deficient ovarian clear cell carcinomas patients." (PMID 36890819, 2023). "For example, in ovarian clear-cell carcinoma, which has a poor prognosis, ARID1A mutations are found in 50% of the tumors, and double mutations in ARID1A and PIK3CA were found in 33% of the tumors." (PMID 38017109, 2023). "The ARID1A gene is reported to be mutated in half of clear cell ovarian cancers and 30% of endometrioid cancers." (PMID 36670456, 2023). "Since ARID1A mutations were described first in gynecologic tumors, it seems as if their role in both endometrioid and clear-cell ovarian cancers is of particular importance." (PMID 37627124, 2023). "Despite ENMD- 2076 did not meet the efficacy bar set in this trial, this AURKA inhibitor has been reported as potentially advantageous for ovarian clear cell carcinomas patients with ARID1A deficiency." (PMID 36890819, 2023). "ARID1A knockout in ovarian clear cell carcinoma (OCCC) RMG1 cells and ARID1A-mutated OCCC cell lines showed defective telomere cohesion, increased telomere damage, and increased chromosomal defects during mitosis." (PMID 38275587, 2023). "It has been reported that a patient with CTNNB1 mutation showed lower immune infiltration in HCC, and ARID1A mutation in ovarian clear cell carcinoma also has a role for immune inhibition, which is consistent with our result." (PMID 35124891, 2022). "Previously, a somatic mutation in ARID1A has been found in 46–57% of ovarian clear cell carcinomas, 30% of ovarian endometrioid carcinomas, and 40% of uterine endometrioid carcinomas." (PMID 35621684, 2022). "ARID1A mutation or loss was associated with immune microenvironmental factors in clear cell ovarian cancer (CCC), suggesting that ARID1A status has potential as a biomarker to guide decisions concerning patient selection for ICB therapy in CCC." (PMID 36389711, 2022). "For example, the AT-rich interactive domain 1A gene (ARID1A) is mutated in over 50% of ovarian clear cell carcinomas and ARID1A mutational status has been shown to correlate with response to an enhancer of zeste homologue 2 (EZH2) inhibitor." (PMID 35739271, 2022). "ARID1A is the most frequently mutated chromatin remodeling gene and is present in many cancers, including but not limited to ovarian clear cell carcinomas, endometrioid carcinomas, bladder cancer and colorectal cancer." (PMID 36435834, 2022). "The combination of a small-molecule inhibitor of the PI3K/AKT pathway (Temsirolimus) with trabectedin (an antineoplastic agent) has shown efficacy in a cohort of patients with ovarian clear cell carcinomas harboring the ARID1A mutation." (PMID 35328145, 2022). "Some studies showed that MMR deficiency is associated with the loss of ARID1A expression in ovarian clear cell carcinoma." (PMID 34680987, 2021). "In contrast, the ARID1A subunit is mutated in approximately 50% of ovarian clear cell carcinoma, 30% of endometrial cancer, 25% of gastric cancer, and 25% of bladder cancer." (PMID 34731603, 2021).